REN (renin)
Diseases named in the same sentence as REN in open-access papers (continued):
Sharing a sentence is not in itself a finding about the gene and the disease.
Hypertension (continued). "Renin–angiotensin–aldosterone system down-regulation by the kidney is mostly dependent on vitamin D. A reduced renin–angiotensin–aldosterone system and anomalies in vascular relaxation brought on by low vitamin D levels may ultimately result in the development of hypertension." (PMID 38068901, 2023). "Nevertheless, some clinical signs could be related to RCC, such as polycythemia, hypercalcemia, hypertension, and Cushing’s syndrome, correlated to erythropoietin, parathyroid-related hormone, renin, and adrenocorticotropic hormone (ACTH) overproduction by cancer, respectively." (PMID 37372161, 2023). "Hypertension is a complex, multifactorial disease state that can involve a combination of pathophysiologic processes, including salt sensitivity, altered arterial compliance, altered vascular reactivity, and altered activity of the renin-angiotensin and adrenergic systems." (PMID 37735420, 2023). "Furthermore, this accumulation could also activate the renin-angiotensin-aldosterone system (RAAS), causing hypertension and increasing insulin resistance, which are recognized renal injury factors." (PMID 36969806, 2023). "Although researchers found a decreasein plasma renin activity in nattokinase group compared to controls, the resultswere not statistically significant, and it was still not known whethernattokinase could prevent the elevation of plasma renin activity levels againstarterial hypertension." (PMID 39076715, 2023). "Women with pre-existing hypertension may continue their current antihypertensive medication, while angiotensin converting enzyme inhibitors, angiotensin II receptor blockers, and direct renin inhibitors are, contraindicated due to adverse fetal and neonatal outcomes." (PMID 36627514, 2023). "Although some studies reported that the circulating renin–angiotensin system is not believed to be directly responsible for the rise in blood pressure, one of the main causes of several types of hypertension has been identified as the disruption of the renin–angiotensin system." (PMID 37887299, 2023). "An enlarged waist suggests increased visceral adiposity, which may contribute to hypertension through mechanisms including the activation of the renin-angiotensin-aldosterone system, activation of the sympathetic nervous system, and physical compression of the kidneys." (PMID 38605973, 2023). "Taken together, these results indicated that renin was activated and released into the circulation to activate the RAAS and participated in the occurrence of hypertension in db/db mice, while, exogenous H2S could reduce the activity, content and release of renin, thus inhibiting RAAS activation." (PMID 36675205, 2023). "Endothelial dysfunction, vascular resistance, the activity of the sympathetic nervous system, renal sodium and fluid retention, and the subsequent renin-angiotensin-aldosterone system may play a crucial part in the etiology of hypertension when insulin resistance is present." (PMID 37273533, 2023). "However, pre-clinical and clinical studies have identified that overactivation of aldosterone/MR and the renin–angiotensin system (RAS) is involved in the pathogenesis of various diseases including hypertension, coronary artery disease, chronic kidney disease, and congestive heart failure." (PMID 36768656, 2023). "In patients with essential hypertension, plasma renin activity may vary." (PMID 36771242, 2023). "Moreover, L-NAME induced hypertension by involving the renin–angiotensin aldosterone system (RAAS)." (PMID 36613225, 2022). "Modest hypertension was found in the hyperuricemia rat model induced by potassium oxonate, which may be due to oxidative stress, decreased nitric oxide availability and activated renin–angiotensin system." (PMID 35656392, 2022). "In addition, renin and Ang-2 can promote the secretion of aldosterone increase, resulting in water and sodium retention, and further increase the blood volume, thereby aggravating hypertension." (PMID 35993052, 2022).
Hypertension (continued). "Mechanistically, a lack of renin suppression that is associated with Vit-D deficiency may exacerbate hypertension." (PMID 35093020, 2022). "The reasons for the higher prevalence of hypertension among men may include the biological factors, differences in sex hormones and activation of the renin-angiotensin system, and behavioral factors such as higher intake of alcohol, which is a risk factor for hypertension." (PMID 35805618, 2022). "As a multifactorial disease, although the current theories of renin-angiotensin-aldosterone system activation, sympathetic nervous system hyperactivity, and renal water and sodium retention are more recognized, it still cannot fully explain the pathological process of hypertension." (PMID 35677431, 2022). "Third, elevated RC levels may be related to hyperinsulinemia and insulin resistance, which might stimulate sympathetic nervous system activity and the renin–angiotensin system, increase renal vascular resistance and renal sodium retention, and thus induce the development of hypertension." (PMID 35222285, 2022). "One ailment that seaweed bioactive compounds may impact is hypertension caused by the enzyme Angiotensin Converting Enzyme 1 (ACE-1; EC 3.4.15.1), found within the Renin-Angiotensin Aldosterone System (RAAS), which causes vasoconstriction of blood vessels, including veins and arteries." (PMID 35741988, 2022). "Hypertension data are most alarming when it is acknowledged that 10–15% of patients have resistant hypertension that requires the use of three different drugs, including an inhibitor of the renin–angiotensin–aldosterone system, a calcium channel blocker, and a diuretic at the highest dose tolerated." (PMID 36356016, 2022). "The link between systemic hypertension and IA might be the renin-angiotensin system (RAS)." (PMID 36449950, 2022). "Furthermore, n-3 PUFA may promote lipid oxidation and enhance energy utilization by altering several key protein expressions and suppressing the renin-angiotensin-aldosterone system to produce a positive outcome in obesity and hypertension." (PMID 35566474, 2022). "In addition to inhibiting NF-κB, direct inhibiting IL-1β, the central pro-inflammatory cytokine in NLRP3 pathway, also obtained the results of attenuating hypertension by the activation of renin-angiotensin system and the generation of ROS in paraventricular nucleus." (PMID 36204568, 2022). "It was first described in 1964 by Paver and Pauline in a young male with severe hypertension and hyperkalemia despite otherwise normal renal function who was further characterized by Stokes and colleagues and Arnold and Healy and shown to have low plasma renin." (PMID 35093948, 2022). "The molecular mechanism of how PRBR reduced hypertension might be (i) the inhibition of the renin–angiotensin axis, (ii) the inhibition of fibrosis, or (iii) the inhibition of oxidative-stress-generating enzymes (NOX) and the activation of an antioxidant enzyme (GPx)." (PMID 36613225, 2022). "Although, some particular clinical features distinguish hypertension in premenopausal period, for instance increased cardiac index and left ventricular ejection time, higher values of resting heart rate, but decreased plasma renin levels, blood volume and total peripheral vascular resistance." (PMID 35722103, 2022). "However, it is unclear whether Ang II/AT1R plays a role in the regulation of macrophage function and whether macrophage Ang II/AT1R signaling is involved in the pathogenesis of low renin SS hypertension." (PMID 35721173, 2022). "However, low-renin activity can be an independent predictor of hypertension in Korean individuals." (PMID 35448080, 2022). "Increased activity of the renin–angiotensin–aldosterone system (RAAS) and sympathetic nervous system (SNS) associated with increased prostaglandin secretion and ROS production were described as additional serious factors contributing to the development of L-NAME-induced hypertension." (PMID 35163364, 2022).
Hypertension (continued). "The pathophysiology of hypertension has yet to be fully elucidated, however proposed risk factors include a high salt diet, insulin resistance, obesity, genetic factors, increased sympathetic nervous system (SNS) activity, renin-angiotensin system activation, and endothelial dysfunction." (PMID 35743756, 2022). "In addition to inducing cognitive impairment through structural and functional impairment of the cerebral blood vessels, hypertension also has a direct impact on the functions of the central nervous system through changes in the cerebral renin–angiotensin system." (PMID 36271341, 2022). "However, this study confirmed the correlation between renin secretion and accessory renal artery diameter and renal artery diameter, providing a new way to study the relationship between accessory renal artery and hypertension." (PMID 35003315, 2021). "Moreover, complex hypertensive milieu (i.e., hypertension, oxidative stress, glomeruli-leaked free fatty acids, and activated renin-angiotensin system) can activate NF-κB signaling, thereby aggravating renal inflammatory actions and accelerates the progression of hypertensive nephropathy." (PMID 34773993, 2021). "This local modulation of Ang II responses may be even more necessary in 2K1C animals, which is a hypertension model that has activation of the renin-angiotensin-aldosterone system due to increased renin secretion by the clipped kidney leading to increases in circulating renin and ANG II levels." (PMID 33897446, 2021). "There is no consensus at this time on the exact mechanisms involved, but viral binding to the ACE2 receptor may lead to an element of renin-angiotensin-aldosterone system disruption that could exacerbate or alter disease presentation in those with pre-existing hypertension." (PMID 33560946, 2021). "Uric acid (UA) may play an important role in the development of hypertension through the following pathophysiological mechanisms: renal afferent artery disease, renin-angiotensin-aldosterone system (RAAS) upregulation, oxidative stress, systemic inflammation, and endothelial dysfunction." (PMID 35087877, 2021). "Animal model data suggested that elevated uric acid could raise the secretion of renin and then activate the renin-angiotensin system, inhibit intrarenal nitric oxide (NO) synthase expression, and reduce NO release, which led to vasoconstriction and a reversible hypertension." (PMID 35071258, 2021). "We hypothesized that RAS gene SNPs that were associated with hypertension and/or decreased efficacy of ACEIs or ARBs as a result of activated RAS, including AT1R rs5186, AT2R rs11091046, REN rs12750834, ANG rs4762, and ANG rs699, could predispose to a higher risk ofnon-invasive BC." (PMID 34898568, 2021). "PRAT reportedly activates the renin-angiotensin system in hypertensive and obese rabbits by applying physical pressure to the surrounding blood vessels, worsening obesity-related metabolic disorders such as hypertension, insulin resistance, and atherosclerosis." (PMID 34298949, 2021). "Furthermore, the presence of hypertension may indicate long-standing renal disease, which can chronically alter renin-angiotensin-system physiology." (PMID 34567562, 2021). "Animal experiments have reported that elevated SUA levels can activate the renin-angiotensin-aldosterone system and the sympathetic nervous system, mediate endothelial dysfunction, and increase oxidative stress and inflammation, resulting in vasoconstriction and hypertension." (PMID 35053631, 2021). "It has been also hypothesized that the hypertension-related immoderate activation of renin-angiotensin-aldosterone system might motivate the NADH/NADPH oxidase system, prompt a massive inflammatory response and cytokine storm, and stimulate vascular cell contraction and constriction." (PMID 34055822, 2021).
Hypertension (continued). "We may infer that specific factors contributed to hypertension on D1, such as activation of the renin-angiotensin-aldosterone system, as described in a study involving dogs with ureteral obstruction, thus increasing renin release and consequent increase in blood pressure." (PMID 34566314, 2021). "Therefore, it may be difficult to distinguish between PA from low-renin essential hypertension, and caution should be taken to interpret CCT results with PAC SP due to the lack of sufficient data on changes in aldosterone levels of EH patients." (PMID 34220715, 2021). "Interestingly, MCMV infection increased the expression of renin in renal cells, suggesting that the renin-mediated increase in the blood volume may contribute to hypertension." (PMID 33245094, 2020). "Additionally, high TG levels are also strongly correlated with insulin resistance, and insulin resistance promotes the development of hypertension by augmenting sympathetic nervous system reactivity, activating the renin-angiotensin system, and stimulating renal tubular sodium reabsorption." (PMID 32293295, 2020). "Indeed, in rats with severe hypertension induced by aortic ligation between the renal arteries, renin is necessary for the pathogenesis of hypertension; however, acute and severe hypertension can damage the endothelium enough to activate plasma pre-kallikrein and increase kinin formation." (PMID 33126450, 2020). "ACE2 is a crucial regulator of the renin-angiotensin system, and plays a regulatory role in the central regulation of blood pressure and cardiovascular function and could become an attractive target for the treatment of hypertension." (PMID 32373340, 2020). "This inhibitory angiotensin II response may be a link in the protective mechanism of omega-3 fatty acids on the cardiovascular system, since alterations in the renin-angiotensin-aldosterone system (RAAS) are involved in the development of arterial hypertension and atherosclerosis." (PMID 32503213, 2020). "There are several factors which may enhance the EVA process such as atherosclerosis via intima–media thickening, smoking through increased production of the reactive oxidative species (ROS), hypertension via activation of the renin–angiotensin system and decreased cell proliferation." (PMID 32118038, 2020). "The possibility has to be considered that a model of hypertension connected with changes in the renin-angiotensin-aldosterone system (RAAS) (the activity of which is modified by the endocannabinoid system) might have revealed a blood pressure-lowering effect of CBD." (PMID 32075117, 2020). "However, it must be noted that blood pressure varies widely and other factors such as the sympathetic nervous system and the renin–angiotensin system, may contribute to arterial hypertension to a higher extent." (PMID 32138278, 2020). "However, we should not conflate the observed associations of hypertension and diabetes with severity of COVID-19 infection as indicative of adverse effects of renin-angiotensin system inhibitors." (PMID 33150129, 2020). "Thus, increased RSNA results in a reduction of renal blood flow and glomerular filtration rate (GFR), an increase in renal vascular resistance and tubular sodium and water reabsorption, and an increased release of renin, contributing to the development and maintenance of hypertension." (PMID 33240096, 2020). "There are several animal models of preeclampsia and pregnancy-induced hypertension that demonstrate evidence of renal injury including the reduced uterine perfusion pressure, the Dahl S rat, the N-nitro-l-arginine methyl ester, and the transgenic renin-angiotensin model of preeclampsia." (PMID 32972452, 2020). "Hence, whether hypertension patients with COVID-19 who are taking renin-angiotensin-aldosterone blockers should change to another class of antihypertensive drug remains controversial." (PMID 32624690, 2020).
Hypertension (continued). "It was also demonstrated previously that a specific RAAS localized in adipose tissue might be crucial for the development of hypertension in this particular population and that there might be a positive correlation between obesity and increased plasma levels of renin, as well as of aldosterone." (PMID 32640705, 2020). "The intrarenal renin-angiotensin system may also contribute to hypertension." (PMID 32625100, 2020). "Importantly, next to differences in immunology between mice and humans, most murine models are hindered by blood pressure differences between intervention and control animals resulting from the sequential induction of hypertension by renin–angiotensin–aldosterone system activation." (PMID 31875423, 2020). "The other explanation could be that the impaired regulation of the renin-angiotensin system, the sympathetic nervous system, and possibly, endothelial factors in patients with poor glycemic control could be a contributing factor for uncontrolled hypertension." (PMID 32637172, 2020). "Therefore, natural compounds that inhibit renin activity could enhance the management of hypertension." (PMID 32610462, 2020). "However, normotensive patients with suppressible aldosterone/renin ratios may frequently develop hypertension and PA." (PMID 32266384, 2020). "These two hits to the renin-angiotensin system could be the primary reason for increased mortality in patients with COVID-19 who have comorbidities with low-degree inflammation such as obesity, diabetes, hypertension, and cancer, or in aged patients." (PMID 33256258, 2020). "Several studies using animal models and cell cultures have identified mechanisms whereby high sUA concentrations might lead to hypertension by reducing endothelial nitric oxide release and activating the renin–angiotensin system leading to smooth muscle cell proliferation." (PMID 31126092, 2019). "When licorice-induced hypertension is treated, it should be kept in mind that it can take up to six months to reverse the mineralocorticoid-like effects of licorice due to its long half-life and the duration required to normalize the renin-angiotensin-aldosterone-system." (PMID 31615045, 2019). "Similarly, renin inhibition with aliskiren improves insulin sensitivity, skeletal muscle glucose uptake, glucose tolerance, and insulin secretion in male rodent models of hypertension, diabetes, obesity, and metabolic syndrome." (PMID 31262355, 2019). "This failure to attenuate hypertension in humans may have been a result of the insufficient neutralization potency by human antibodies against pig renin because other studies indicated that antibodies against pig renin have little effect on human renin." (PMID 31485348, 2019). "However, conclusions that chronic TZD failed to elevate renin activity/angiotensin II levels are complicated by the underlying varied relationship between hypertension and plasma renin activity." (PMID 31543812, 2019). "Hence, prorenin/renin levels in circulation may be altered in response to stimuli like hypertension, sodium ion concentrations, pharmacological agents including ACE-I, ARBs, loop diuretics, and others." (PMID 31261774, 2019). "Gap junctions play a role in the renin-angiotensin system, tubuloglomerular feedback, and salt and water reabsorption and, as a consequence, help regulate blood pressure, and they could be involved in hypertension and diabetes." (PMID 31100850, 2019). "Unfortunately, none of the antihypertensive agentscould significantly reduce perinatal mortality.Continuation of current medication except for angiotensin-converting enzyme (ACE) inhibitors, ARBs,and direct renin inhibitors may be the best strategy incases with pre-existing hypertension." (PMID 29707923, 2018).